GREM2 (gremlin 2, DAN family BMP antagonist)
Diseases named in the same sentence as GREM2 in open-access papers (continued):
Sharing a sentence is not in itself a finding about the gene and the disease.
Obesity (2 papers, 2023 to 2025). Accumulation of substantial excess body fat. "Circulating Gremlin 2 (Grem2) has recently been linked to human obesity, but its role in type 2 diabetes (T2D) remains unclear." (PMID 40270326, 2025). "Intriguingly, although we previously showed that fasting Grem2 levels are linked with obesity, the relationship between circulating Grem2 and β‐cell function was independent of BMI." (PMID 40270326, 2025).
postmenopausal osteoporosis (2 papers, 2020 to 2025). Metabolic disorder associated with fractures of the femoral neck, vertebrae, and distal forearm. "GREM2 rs11588607 polymorphism exhibited negative correlation with the risk of postmenopausal osteoporosis under five models." (PMID 32297643, 2020).
type 2 diabetes (2 papers, 2025). "The level of circulating Grem2 has been observed in patients with central obesity and visceral adiposity, which are known risk factors for type 2 diabetes." (PMID 41465472, 2025). "It was shown that fasting levels of circulating Grem2 are significantly lower in patients with type 2 diabetes compared to a healthy control group." (PMID 41465472, 2025).
anaplastic meningioma (1 paper, 2024). A WHO grade III meningioma characterized by the presence of malignant morphologic features, including malignant cytology and a very high mitotic index (20 or more mitoses per ten high power fields). "Forced expression of GREM2 in anaplastic meningioma (IOMM-Lee, HKBMM) and subsequent proliferation assay found that GREM2-expressing cells showed decreased proliferation rate." (PMID 38446374, 2024).
Anxiety (1 paper, 2024). Intense feelings of nervousness, tension, or panic often arise in response to interpersonal stresses. "Grem2−/− mice exhibited increased anxiety on the elevated zero maze in response to acute and chronic stress." (PMID 39349059, 2024). "We documented a sex-specific role of Grem2 in anxiety under chronic stress conditions." (PMID 39349059, 2024). "It appears that males are more reliant on Grem2 in mitigating anxiety in response to stress." (PMID 39349059, 2024). "Therefore, it is likely that the increase in BMP signaling and decrease in hippocampal NSC proliferation seen in Grem2−/− mice contributes to heightened anxiety phenotypes." (PMID 39349059, 2024). "Furthermore, we found increased stress-induced anxiety and seizure susceptibility phenotypes in mice lacking Grem2." (PMID 39349059, 2024). "We show that in correspondence with evident NSC proliferative deficits, stress-induced anxiety is significantly increased in the absence of Grem2." (PMID 39349059, 2024). "Furthermore, the lack of Grem2 contributes to the development and progression of neurogenesis-related disorders such as anxiety and epilepsy." (PMID 39349059, 2024). "Importantly, lack of Grem2 is correlated with neurogenesis-related neurological disorders, such as anxiety and epilepsy." (PMID 39349059, 2024).
bipolar disorder (1 paper, 2019). A disorder of the brain that causes unusual shifts in mood, energy, activity levels and the ability to carry out day-to-day tasks. "Increased predicted expression of GREM2 in testis was the most associated (P = 2.20 × 10−5) gene-tissue pair with bipolar disorder." (PMID 31579629, 2019).
Crohn disease (1 paper, 2024). A gastrointestinal disorder characterized by chronic inflammation involving all layers of the intestinal wall, noncaseating granulomas affecting the intestinal wall and regional lymph nodes, and transmural fibrosis. "A study showed that Grem1+ Grem2+ myofibroblasts highly express COL18A1 and COL23A1 mRNA in the ileum of patients with Crohn’s disease." (PMID 39327633, 2024). "Myofibroblast reprogramming into Grem1+ Grem2+ cells is induced by CHMP1A, TBX3, and RNF168, which might contribute not only to wound healing but also fibrosis in Crohn’s disease." (PMID 39327633, 2024).
diabetic nephropathy (1 paper, 2025). "Furthermore, according to several studies, Grem2 is associated with the progression of diabetic nephropathy caused by podocyte apoptosis." (PMID 41465472, 2025).
gastric cancer (1 paper, 2020). A primary or metastatic malignant neoplasm involving the stomach. "Silencing GREM2 can inhibit the JNK signaling pathway in gastric cancer, which inhibits tumor growth." (PMID 33299869, 2020).
metastatic prostate carcinoma (1 paper, 2023). A carcinoma that arises from the prostate gland and has spread to other anatomic sites. "Unlike ligands, soluble antagonists in metastatic prostate cancer patients are consistently increased in patients with CHRD at 12%, NOGGIN, SOSTDC1, FSTL1 at 7% and GREM2 at 6% of patients." (PMID 36054271, 2023).
myocardial infarction (1 paper, 2024). Gross necrosis of the myocardium, as a result of interruption of the blood supply to the area, as in coronary thrombosis. "Indeed, GREM2-dependent control of BMP2 availability affects the extent of immune cell infiltration and maintenance of heart function during experimental myocardial infarction in Grem2-deficient mice." (PMID 39196111, 2024).
non-alcoholic fatty liver disease (1 paper, 2025). "It has been reported that SGLT2i can decrease miRNA-34a-5p expression, which can induce downregulation of GREM2 to inactivate hepatic stellate cells of non-alcoholic fatty liver disease." (PMID 41446634, 2025).
oligoarticular JIA (1 paper, 2022). "LRRC15, GREM1, and GREM2 are overexpressed in chondrocyte-like cells from persistent oligoarticular JIA FLS compared to pre-extension oligoarticular JIA FLS." (PMID 36167601, 2022).
Prediabetes (1 paper, 2025). "In consistency, for participants with prediabetes, even in the insulin‐compensated state, higher 1‐h Grem2 levels were associated with better β‐cell function indicated by the oral DI independent of age, sex, and adiposity before calorie restriction." (PMID 40270326, 2025). "We further examined changes in Grem2 levels in response to oral antidiabetic drugs in participants with T2D in Trial 2 (n = 67) and calorie restriction in participants with prediabetes in Trial 3 (n = 231)." (PMID 40270326, 2025).
renal fibrosis (1 paper, 2024). A final common manifestation of a wide variety of chronic kidney diseases characterized by glomerulosclerosis and tubulointerstitial fibrosis. "The increased expression levels of renal fibrosis-related genes (Grem2, Id3, Fst, Dcn) and renal damage-related genes (Runx1, Vtn, Clo6a2, Tnxb, Itga8, Timp2, Fgfr2, Fgf9) further supported the idea that miPEP31 deficiency exacerbated Ang II-induced kidney inflammation." (PMID 38992718, 2024).
soft tissue sarcoma (1 paper, 2024). A malignant neoplasm arising from muscle tissue, adipose tissue, blood vessels, fibrous tissue, or other supportive tissues excluding the bones. "Compared to non-metastatic patients, the GREM2 and CTSS genes exhibited significantly higher expression levels, while TINAGL1, ACKR1, and HLA-DRB1 showed a tendency to increase in metastatic soft tissue sarcoma (SS); however, these differences were not statistically significant." (PMID 39735532, 2024).
tendinopathy (1 paper, 2022). "GREM2 is a BMP antagonist that is regulated by the circadian clock; GREM2 has been linked to the development of tendon calcification and the development of tendinopathy." (PMID 35866615, 2022). "Other candidate tendinopathy genes associated with breed group differences in DSLD risk identified in this study include PRDX2 and GREM2." (PMID 35866615, 2022).
tooth agenesis (1 paper, 2019). A tooth disease characterized by failure to develop one or more missing teeth. "The genetic polymorphism of axin 2 (AXIN2) and Gremiln-2 (GREM2, also called PRDC) were related with tooth agenesis." (PMID 31133012, 2019).
cancer (13 papers, 2019 to 2025). A tumor composed of atypical neoplastic, often pleomorphic cells that invade other tissues. "Although GREM1 has been reported to be involved in promoting various cancers, little has been reported about effects of GREM2 on cancer." (PMID 37880751, 2023). "However, as an inhibitor of adipogenesis, the role of GREM2 in cancer progression is not well understood yet." (PMID 37880751, 2023). "However, the role of GREM2 in cancer progression is not well understood yet." (PMID 37880751, 2023). "Given that GREM2’s functions have not been studied in cancer, our results need to be verified by experiments." (PMID 30755833, 2019).
tumor (11 papers, 2019 to 2025). "Specifically, exosomally delivered miR-423-5p promotes tumor cell survival via the TGF-β/GREM2 axis." (PMID 41154598, 2025). "RNA was extracted from tumor tissue, and the expression of DEIRGs including GREM2, CTSS, TINAGL1, ACKR1, HLA-DRB1, and STC2 was verified using real-time quantitative reverse transcription PCR (RT-qPCR)." (PMID 39735532, 2024). "The inhibition of miR-423-5p in vivo prevented tumor growth, tumor weight, and taxane resistance and increased GREM2 expression." (PMID 37237523, 2023). "In contrast genes involved in development and differentiation (Arid5b, Inmt, Grem2, Gdap10), cell metabolism (Alas1, Gsta1, Thrsp, Fdft1, Elovl6), tumor growth (SerpinA4, Cish, Rpl36), and cell cycle control (PLK3, Myc, HNF6/Onecut1) were downregulated." (PMID 33004985, 2020). "However, IL-6 administration increased both the size of primary tumor and the number of metastatic lung lesions, which were reduced by adipocytes-Grem2." (PMID 37880751, 2023). "In addition, we have identified novel potential regulators of tumor progression, including the GREM2 and snoRNAs genes." (PMID 31039818, 2019). "GREM2, which belongs to the DAN family, regulates tumor development by regulating bone morphogenetic proteins and making them interact with each other." (PMID 36983630, 2023). "Consistent with the growth outcome of the primary tumor, mice injected with MTV/TM-011 cells and adipocytes-Grem2 had less lung metastases than mice injected with MTV/TM-011 cells and adipocytes-mock." (PMID 37880751, 2023).
infection (1 paper, 2022). The state of being infected such as from the introduction of a foreign agent such as serum, vaccine, antigenic substance or organism. "Moreover, the absence of the IFNγR rescued infection-driven BMP alterations: we found no loss of Bmp2 or Id1 expression, but reduced Grem2 expression in infected IFNγR KO mice compared to WT littermates." (PMID 35332152, 2022).
GREM2 also shares sentences with these, for which no sentence is quoted: atrial fibrillation (2 papers); angiosarcoma (1); Arrhythmia (1); catecholaminergic polymorphic ventricular tachycardia (1); central obesity (1); clear renal cell carcinoma (1); epilepsy (1); kidney damage (1); long-QT syndrome (1); malignant meningiomas (1); myocardial inflammation (1); neuroblastoma (1); Oligodontia (1); ovarian endometriosis (1); pulmonary arterial hypertension (1); Seizure (1); short QT syndrome (1); skeletal system disease (1).